TLR4 (toll like receptor 4)
Diseases named in the same sentence as TLR4 in open-access papers (continued):
Sharing a sentence is not in itself a finding about the gene and the disease.
tumor (continued). "In our whole population-based study of NPC in Finland, we examined the expression of TLR1, TLR2, TLR4, TLR5, TLR7, and TLR9 in 150 tumours and analysed their pattern of expression according to EBV and HPV status, and clinical outcome." (PMID 31238894, 2019). "RPS3 induces maturation and activation of dendritic cells, acting as a new ligand for TLR4 in the innate immune system, and significantly increases CD8+ T cell production in the presence of a tumor-specific antigen in the adaptive immune system." (PMID 30819254, 2019). "When TLR4 or MD-2 was inhibited using shRNA in SGC7901 cells, LPS-induced tumor growth was considerably restrained in the knockdown groups compared with the scrambled shRNA group." (PMID 30636642, 2019). "Toll like receptor 4 (TLR4) is a chief receptor for bacterial LPS that overexpresses in CRC and plays a vital function in tumor development." (PMID 31635333, 2019). "The binding of a natural ligand, Hsp105, found on the surface membrane of tumor-derived exosomes to TLR2 and TLR4, stimulates the secretion of IL-6 and PGE1." (PMID 31555295, 2019). "However rhCNB did not cause any obvious inhibition of tumor growth in the TLR4−/−mice." (PMID 31218844, 2019). "When administered to TLR4-expressing DC in vitro, HMGB1 augments the expression of pro-IL-1β and prevents the lysosomal degradation of engulfed tumor antigens, which is a major prerequisite for efficient cross-presentation." (PMID 29462947, 2018). "Stimulation of these cells with a TLR4 agonist triggers the release of GZMB and cancer cell demise, probably at the origin of in vivo tumor regression." (PMID 29983866, 2018). "S100A8/A9 homo/heterodimers can interact with the tumor cell surface receptors like RAGE and TLR4 resulting in the activation of MAPK and NF-κB signalling pathways, which promotes tumor growth and invasion." (PMID 29568375, 2018). "TLR4 is one of the most studied members of the TLR family and it has been involved in inflammation and resistance to virus, as well as in tumor microenvironment." (PMID 29679017, 2018). "Cooperation between TLR4 signaling and STAT3 in promoting tumor-initiating stem-like cells in mouse liver was recently reported." (PMID 30034633, 2018). "The mechanism of tumor cell survival, expansion and metastasis is binding to TLR-2, TLR-4, TLR-9 and RAGE, which mediates HMGB1-dependent activation." (PMID 30526680, 2018). "Tumor cells release soluble mediators like ADP, thromboxane A2 (TXA2), or high-mobility group box 1 (HMGB1), which ligates with toll-like receptor 4 (TLR4) to instigate a local platelet activation." (PMID 30305116, 2018). "TLR4 and TLR5 stimulation reportedly activate cancer cell proliferation and promote tumor formation by various cancer cells." (PMID 30410674, 2018). "The tumor cells were positive for PAUF as a cytoplasmic pattern, whereas TLR4 showed membranous and cytoplasmic expression pattern." (PMID 30111860, 2018). "Although CIS therapy was more effective than P-MAPA in reducing the tumor size, P-MAPA immunotherapy significantly increased the expressions of TLR2 and TLR4." (PMID 29343281, 2018). "We evaluated TLR2, TLR4 and TNF-α mRNA expression in peritoneal macrophages and serum TNF-α protein levels at a single time-point after tumor induction and after therapeutic intervention with zymosan." (PMID 29588627, 2018). "Furthermore, we demonstrated, for the first time, an interesting TLR-4/Wnt modulation, suggesting that combined therapies that simultaneously enhance Wnt/Dkk-3/claudin-5 activity and inhibit TLR-4 pathway, might shift the balance from tumor growth stasis to cytotoxic therapeutic responses." (PMID 30680070, 2018). "TLR4 and 9 were also assessed in OSCC, and these receptors were found to have elevated expression levels which were correlated with tumor development." (PMID 29854832, 2018).
tumor (continued). "Our combined data from the TLR4 knockout model and ATOR treatment clearly shows that TLR4 plays an essential role in mediating tumor-induced AT remodeling and cachexia development." (PMID 30575787, 2018). "However, in the TLR4−/− TB mice there was no weight loss, without any differences in tumor growth." (PMID 30575787, 2018). "To understand the effects of the treatments, we assessed the tumor size, histopathology, and the TLR2- and TLR4-mediated inflammatory responses." (PMID 29343281, 2018). "TLR4 is a cancer stem cell marker in HCC, and TLR4 expression increases tumor-initiating activity and chemoresistance during HCC development." (PMID 29338742, 2018). "The increased expression of TLR4 and ERK1/2 reveals immune response and tumor progression, respectively, and their ultimate decrease is an indicator of nerve damage." (PMID 29637027, 2018). "Although CIS therapy was more effective than P-MAPA in reducing tumor growth, P-MAPA immunotherapy significantly increased the expressions of TLR2 and TLR4." (PMID 29343281, 2018). "The increased expression of TLR4 and ERK1/2 reveals earlier immune response and tumor progression, respectively, and their ultimate decrease is an indicator of nerve damage." (PMID 29637027, 2018). "Next, we tested the ability of in vitro TLR4-differentiated M-LECP to integrate and increase the density of tumor-induced lymphatic vessels." (PMID 28598999, 2017). "TLR4 is a member of the toll-like receptor (TLR) family, which promotes tumor growth, metastasis and immune escape." (PMID 29228698, 2017). "Positive staining for TLR4 and TLR8 was observed in macrophages around the periphery of the tumors, but sparse staining was observed within the tumor itself." (PMID 29190881, 2017). "APS and LPS were found to significantly induce the expressions of mRNAs and proteins of TLR4, TRAF-6, NF-κB and AP-1 in the TLR4+/+ tumor-bearing mice, compared with those in the NS group (P < 0.05)." (PMID 28303957, 2017). "Inversely, there was no remarkable differences in the expression of mRNA and proteins of TLR4, TRAF-6, NF-κB and AP-1 among groups in the TLR4−/− tumor-bearing mice (P > 0.05)." (PMID 28303957, 2017). "High expression levels of TLR4 and OPN were detected in HO-8910PM cells, which promoted the proliferation, migration and invasion of tumor cells." (PMID 29228698, 2017). "Although M1 macrophages has anti-tumor function, our data shows markers including CD68, CD86, TLR2 and TLR4 are correlated with CD163 too." (PMID 29152078, 2017). "In the current study, we show that DC matured in the presence of a combination of IFNγ and ligands for TLR3 (poly I:C), TLR4 (LPS), and TLR8 (R848) display features crucial for triggering efficient T cell-mediated anti-tumor responses." (PMID 28601925, 2017). "The enhanced activation of ERK1/2 in biglycan-stimulated tumour cells was abolished by preincubation with U0126 or TLR2 and/or TLR4 inhibitors." (PMID 27295191, 2016). "Passively released HMGB-1 binds to receptors such as Toll-like receptor 4 (TLR4) with high affinity, and binding of HMGB-1 to TLR4 can activate NF-κB light chain, which play important roles in tumor growth and progression." (PMID 26872033, 2016). "TGF-β1 produced from whole tumor cells decreases antitumor immunity by DC-tumor FCs even when TLR2 and TLR4 are co-administered." (PMID 27240347, 2016). "Biglycan protein enhanced tumour cell migration and this was inhibited by neutralizing the biglycan receptors using an anti-TLR2 or anti-TLR4 antibody." (PMID 27295191, 2016). "The expression of TLR4 has been correlated with resistance of human OSCC to chemotherapy, and TLR2 expression was shown to be highly correlated with tumor progression." (PMID 27191981, 2016). "The presence of soluble decoy receptors like soluble TLR2 and TLR4 and the down-regulation of TLR expression by anti-inflammatory cytokines, such as TGF-β and IL-10 are the most likely functional mechanisms in the tumor environment." (PMID 25682197, 2015).
tumor (continued). "Anti-TLR4 and anti-RAGE pretreated tumor cells, however, lost the protective ability of HMGB1, as compared to HMGB1-treated tumor cells with control IgG." (PMID 26469759, 2015). "Treatment of tumor cells by ICD-inducing cytotoxic compounds leads to a post-apoptotic release of HMGB1, which is recognized by TLR4 on DCs." (PMID 26483791, 2015). "In vivo, the activation of TLR4 and TLR4-downstream molecules (TRAF6, NF-κB and AP-1) in spleens of B10 (TLR4+/+) and ScCr (TLR4−/−) tumor-bearing mice were measured by Q-PCR and Western blot." (PMID 26032186, 2015). "LPS translocation after irradiation is responsible for the activation of antigen presenting dendritic cells (DC) via TLR4 signaling, which in turn are able to efficiently activate CD8+ T cells and enhance tumor rejection." (PMID 26075613, 2015). "Then, we characterized the ability of these recombinant FN fragments to agonize TLR4, activate DCs, stimulate CD8+ T cell expansion, and induce functional CTLs, where functionality was judged by cytotoxicity in a tumor vaccine model." (PMID 25708982, 2015). "As BLS has a direct effect in B16 cells via TLR4, it is expected that BLS treatment would be successful only when TLR4 is expressed in most tumor cell population." (PMID 25973756, 2015). "Use of both anti-TLR4 and anti-RAGE had a more deleterious effect on tumor cells, suggesting that both receptors confer HMGB1-mediated drug resistance to DTX." (PMID 26469759, 2015). "Using prostate cancer as a focus, where acquired resistance to docetaxel (DTX) signifies a point of no return for patients, we demonstrate that DTX acts by a paracrine mechanism to promote tumor cell survival and outgrowth via a HMGB1/TLR4-RAGE/sCLU pathway." (PMID 26469759, 2015). "Further complicating the issue is the fact that specific family members, such as TLR2, TLR4, and TLR9, following detection of corresponding TLR agonists, have a tumor promoting role in the biology of these tumors." (PMID 25411122, 2014). "TLR4 and MyD88 were expressed in human OSCC cell lines and expression level correlated with tumor differentiation, with higher expression in more well-differentiated carcinomas." (PMID 25309546, 2014). "Therefore, activating TLR4 from cancer cells could promote tumor metastasis." (PMID 25299052, 2014). "TLR4 activation was shown to suppress TGF-beta signaling and promote chemoresistance in tumor-initiating cells of virus-induced hepatocellular carcinoma." (PMID 24723911, 2014). "Analysis of tumor cells from sorted bone marrow mononuclear cells of MM patients showed high TLR2, TLR4 and TLR9 mRNA levels and these findings were consistent with the high protein expression of TLR4 and TLR9 when analyzed by flowcytometry." (PMID 25112836, 2014). "Overexpression of miR-511-3p in BM-derived cells inhibits tumor growth; it is downregulated in CRC; it also is a putative positive regulator of Toll-like receptor 4 and initiator of innate immune response." (PMID 25594007, 2014). "TLR4 signaling was activated and a variety of immune cell types, including CD4+ T, CD8+ T, NK cells, and macrophages, were exploited in tumor suppression." (PMID 25411122, 2014). "For example, TLR4-primed MSCs have an antitumor effect, whereas TLR3-primed MSCs promote tumor growth and metastasis." (PMID 24971369, 2014). "In this mechanism, HSP90 binds to TLR4, which leads to activation of EGFR and an increase in intracellular calcium levels necessary to promote tumor cell migration." (PMID 25411122, 2014). "HMGB1 aids in the recruitment of endothelial precursor cells (EPC) using RAGE and TLR2/TLR4 in c-kit-positive EPC, thus, contributing to tissue repair and tumor growth." (PMID 24723911, 2014). "Proliferation of tumor cells in response to LPS in A549 cells was induced by the ligation of LPS to CD14 and the pattern recognition receptor TLR4 followed by COX-2-dependent PGE2 synthesis." (PMID 22923191, 2013).
tumor (continued). "In conclusion, this is the first study to demonstrate that LPS effectively induces tumor growth in various experimental models of NSCLC in vitro, ex vivo and in vivo via CD14-, TLR4-, EGFR- and COX-2-signaling." (PMID 22923191, 2013). "On the other hand, it has been observed that S100A9 homodimers interacted with TLR4 and RAGE, which are two receptors involved in the control of tumour growth in different systems." (PMID 23626736, 2013). "We conclude from these data that a chemical probe selected only for its ability to bind S100A9 and inhibit its interaction with TLR4 and RAGE, show anti-tumor activity in vivo." (PMID 23667563, 2013). "The second is the secretion of an endogenous Toll-like receptor 4 (TLR4) ligand High-mobility group box 1 (HMGB1), which is required for efficient processing of tumor antigen by dendritic cells." (PMID 23762310, 2013). "One mechanism of achieving this enhanced T-cell activation following tumor irradiation is via the secretion of the HMGB1 protein by dying irradiated tumor cells and binding of HMGB1 on TLR4 expressed by dendritic cells." (PMID 24324970, 2013). "We show that DC/tumor activated with combined TLR2 and TLR4 are most effective inducer of MUC1-specific CTL activation compared with solitary TLR2- or TLR4-activated DC/tumor on a per fusion cell basis." (PMID 23555011, 2013). "Thus, both S100A9 and its receptor TLR4 may be involved in tumor development." (PMID 22470535, 2012). "Protective immunization in this scenario was dependent on the presence of TLR4 on DCs and its ligand HMGB1, both released by tumor cells following RT." (PMID 23251903, 2012). "Our results indicate that TLR4 signaling is required for LPS-induced EMT, tumor cell invasion and metastasis, which provide molecular insights for LPS-related pathogenesis and a basis for developing new strategies against metastasis in HCC." (PMID 22938142, 2012). "This conclusion was supported by the finding that ABR-215050, a small molecule inhibitor of the S100A9/TLR4 interaction, significantly inhibited EL4 tumor growth." (PMID 23234398, 2012). "Binding of Prx1 to TLR4 stimulates release of pro-inflammatory cytokines interleukin (IL)-6 and tumor necrosis factor (TNF)-α from macrophages and VEGF from tumor cells, macrophages and endothelial cells." (PMID 23185615, 2012). "HMGB1 is able to bind to the toll-like receptor 4 (TLR4) on DC, which allows tumor-derived antigens to be processed and presented along with MHC and costimulatory molecules on the surface of DC." (PMID 22927872, 2012). "Expression of TLR4 was confirmed by RT-PCR and FACS analysis on a large number of murine tumor cells, such as colon, breast, prostate, lung, and melanoma cancer cells." (PMID 22110526, 2011). "In particular, abundant tumor cell-derived substances like hyaluronan fragments together with heat shock proteins are endogenous ligands to TLR2 and TLR4 and trigger M2-like cytokine profile in macrophages." (PMID 21760797, 2011). "When the TLR4/TLR9 agonist complex is applied after tumor cell inoculation, it is unable to reverse the immunosuppressive tissue environment induced by tumor cells." (PMID 21931823, 2011). "Interaction of TLR4 binding partners, which have been secreted by tumor cells (so-called danger signals, e.g. HMGB1) activate leukocytes through the differential engagement of multiple surface receptors like TLR4 and RAGE." (PMID 21854645, 2011). "TLR4 expression has also been described on tumor cells of HNSCC, where its level of expression correlates with tumor grade." (PMID 21854645, 2011). "Exposure of tumour cells to oxaliplatin results in the release of high mobility group box 1 (HMGB1) protein, that activates DCs in a toll-like receptor-4 (TLR4)-dependent manner." (PMID 20924373, 2010). "In a different model, tumor incidence, multiplicity and size were reduced after azoxymethane (AOM) and DSS treatment when TLR4 was ablated in mice via reduction of TLR4 expression and signaling in IEC." (PMID 20885960, 2010).
tumor (continued). "We previously demonstrated that TLR4 protects against BHT-induced chronic pulmonary inflammation and tumor promotion." (PMID 19925653, 2009). "LPS promotes tumour cell ECM adhesion and invasion through activation of the u-PA system in a TLR-4- and NF-κB-dependent manner." (PMID 19436306, 2009). "In conclusion, bacterial endotoxin directly promotes tumour cell adhesion and invasion through the upregulation of u-PA and u-PAR mediated by TLR-4-dependent activation of NF-κB." (PMID 19436306, 2009). "TLR-4 and NF-κB inhibition ameliorated LPS-enhanced u-PA and u-PAR expression, tumour cell vitronectin adhesion and ECM invasion." (PMID 19436306, 2009). "For example, lipopolysaccharide (LPS) from Gram-negative bacteria activates TLR4–NF-κB/MAPK signaling in tumor cells, thereby promoting cancer cell survival and proliferation." (PMID 41602751, 2026). "For instance, LPS in the outer membrane of Gram-negative bacteria activates the host's cell-surface TLR4, thereby triggering a T cell-mediated response against tumor cells." (PMID 41486167, 2026). "Mechanistically, the cathepsin C in tumor debris generated by anticancer therapy is phagocytosed by macrophages and drives CXCL1/2 and complement factor B production via activating the TLR4/NF-κB signaling pathway, subsequently promoting NETosis and impairing therapeutic efficacy." (PMID 41480760, 2026). "Given that TLRs are closely related to tumor development and grade, we explored whether there is any difference in TLR2 and TLR4 expression patterns between LGGs and HGGs." (PMID 40809181, 2025). "Therefore, we make the TLR4/NF-κB/NLRP3 inflammasome as the main line, supplemented by serum inflammatory factors, peripheral blood cell typing, tumor cell proliferation and apoptosis indicators to explore the anti-EC effect of Ori in this study." (PMID 40606986, 2025). "Furthermore, downregulating LINC00886 reduces the expression of TLR4, Myd88, phosphorylated NF-κB p65, and PD-L1, while increasing TNF-α and IFN-γ levels and enhancing CD8 + T cell antitumor activity, thereby reducing tumor cell immune escape." (PMID 40999508, 2025). "Thus, TLR4 and HMGB1 play a critical role in the cross-presentation of tumor antigens from dying tumor cells by DCs to CD8+ T cells." (PMID 40362678, 2025). "Moreover, PSP enhanced immune function by activating the TLR4–MAPK/NF-κB pathway, thereby promoting cytokine secretion and facilitating tumor cell clearance." (PMID 41293256, 2025). "In lung adenocarcinoma models, radiotherapy induces tumor cells to release HMGB1, which activates CAFs through the TLR4/PI3K/AKT pathway—driving conversion to the myCAFs phenotype with upregulated FAP, α‐SMA, and Collagen I expression, thereby enhancing tumor fibrosis and invasiveness." (PMID 41354099, 2025). "In the tumor microenvironment, extracellular HMGB1 increases various inflammatory cytokines and chemokines and promotes tumor growth, angiogenesis, and metastasis through TLR4 and RAGE." (PMID 40389855, 2025). "TLR4 signaling promotes tumor growth, while TLR7, TLR8, and TLR9 signaling may exert anti-tumor effects." (PMID 40948759, 2025). "Moreover, SMF has shown the potential to synergize with clinically established TLR-4 agonists (e.g., MPLA) and immune checkpoint blockers such as anti-PD-L1, thereby further augmenting anti-tumor effects." (PMID 40487409, 2025). "In summary, HMGB1 activates multiple inflammatory factors in TME by activating signaling pathways such as RAGE, TLR4, and PI3K, thereby promoting tumor growth, facilitating cellular invasion and metastatic spread, while concurrently contributing to therapeutic resistance in cancer treatment." (PMID 40969278, 2025). "This process is driven by DAMPs released by tumor necrosis: for example, HMGB1 recruits neutrophils to the necrotic area by activating the TLR4/NF-κB pathway, forming a positive feedback loop of “necrosis-DAMP-TAN infiltration” that further amplifies the ferroptosis effect." (PMID 40535125, 2025).